HDC (histidine decarboxylase)
Description:
Catalyzes the biosynthesis of histamine from histidine.
Tractability: Small molecule: a structure with a bound ligand is known; it belongs to a druggable protein family.
Target class: Enzyme; Lyase
Gene: Protein-coding gene on chromosome 15 (50,241,947 to 50,265,965, reverse strand). Ensembl gene ENSG00000140287.
Subcellular location (Human Protein Atlas): Nuclear bodies
Pathways (Reactome):
Metabolism: Histidine catabolism
Gene Ontology:
Molecular function: histidine decarboxylase activity; protein binding; carbon-carbon lyase activity; carboxy-lyase activity; pyridoxal phosphate binding
Biological process: histamine biosynthetic process; L-histidine catabolic process; amino acid metabolic process; biogenic amine biosynthetic process
Cellular component: cytosol
Genetic constraint (gnomAD): Loss-of-function variants: 28 observed, 63.35 expected, observed/expected ratio (o/e) 0.44, 90% interval 0.33 to 0.61. The upper end of that interval is the gene's LOEUF score, 0.61, which puts it in group 2 of 6, group 1 being the genes least tolerant of losing a copy. Missense variants: 689 observed, 852.42 expected, observed/expected ratio (o/e) 0.81, 90% interval 0.76 to 0.86. Synonymous variants: 303 observed, 327.82 expected, observed/expected ratio (o/e) 0.92, 90% interval 0.84 to 1.02.
Homologues: Orthologues: chimpanzee HDC (99% identical), macaque HDC (98% identical), dog HDC (93% identical), pig HDC (91% identical), rabbit HDC (89% identical), guinea pig HDC (87% identical), mouse Hdc (87% identical), rat Hdc (86% identical), tropical clawed frog hdc (72% identical), zebrafish hdc (52% identical), Drosophila melanogaster Hdc (49% identical), Caenorhabditis elegans hdl-2 (15% identical). Paralogues in human: DDC (37% identical), GAD1 (18% identical), GAD2 (17% identical), GADL1 (16% identical), PDXDC1 (16% identical), CSAD (15% identical), SGPL1 (10% identical).
Diseases named in the same sentence as HDC in open-access papers:
HDC is named in the same sentence as 72 diseases in open-access papers, as found by Europe PMC text mining. Sharing a sentence is not in itself a finding about the gene and the disease. The quoted sentences say what the papers report.
Allergy (9 papers, 2016 to 2025). An allergy is an immune response or reaction to substances that are usually not harmful. "Histamine is generated by the decarboxylation of histidine by histidine decarboxylase, and therefore histidine is often closely associated with allergic diseases." (PMID 38378549, 2024). "Thus, the present study aimed to evaluate the anti-allergic effect of camu-camu fruit extract by inhibiting mast cell degranulation and targeting novel therapeutic strategies for activation of H1R, H4R, and HDC through the underlying molecular mechanisms of A23187-induced allergies in RBL-2H3 cells." (PMID 35052608, 2021). "First, isolated MVs (without SAEW treatment) prepared in a mixed ratio of 1:0 were added to RBL-2H3 cells, and the mRNA expression levels of the allergy-related genes HDC, FcεR1α, IL-4, and TNF-α were examined." (PMID 38282743, 2023). "The HDC inhibitors are henceforth thought to be beneficial through the reduction of potentially damaging histamine-related local immune responses in allergic diseases." (PMID 35743851, 2022). "Allergy is an immunological disorder that develops in response to exposure to an allergen, and histamines mediate these effects via histidine decarboxylase (HDC) activity at the intracellular level." (PMID 33261109, 2020). "Compounds that inhibit HDC activities will represent a new target for the treatment of allergic diseases." (PMID 33261109, 2020). "They examined the effect of lipopolysaccharide (LPS) on allergies to Ni and other metals in mice, and concluded that LPS is a major inducer of metal allergies and potently promotes such allergies via innate immunity and histidine decarboxylase (HDC) induction in cells." (PMID 26771600, 2016). "Thus, HDC serves as an important therapeutic target in allergic diseases." (PMID 35743851, 2022). "Histamine, converted from histidine by histidine decarboxylase (HDC), mediates allergy and inflammation by activating histamine receptors." (PMID 34679659, 2021).
Tourette syndrome (9 papers, 2015 to 2022). A neurologic disorder caused by defective metabolism of the neurotransmitters in the brain. "A nonsense heterozygous mutation (p.Trp317Stop) in the HDC gene was identified in a two-generation pedigree: the father and eight children carrying the variant in heterozygosity were affected by Tourette Syndrome." (PMID 36292569, 2022). "The HDC gene has been previously associated with Tourette Syndrome (TS)." (PMID 36292569, 2022). "In addition, functional mutation in the HDC gene resulting in deficits of the histaminergic neuronal system has been linked to the mechanism and modulation of Tourette’s syndrome and tics." (PMID 25899065, 2015). "PhenPathTOOL correctly recognizes that the concomitance of phenotypes points to the Tourette syndrome, and to two genes (SLITRK1, HDC) that are associated with the disease." (PMID 31307376, 2019). "A loss-of-function mutation of the histidine decarboxylase (HDC) gene (EC 4.1.1.22), the essential enzyme for histamine production, is associated with Tourette’s syndrome." (PMID 30744146, 2019).
breast carcinoma (5 papers, 2014 to 2024). "In this regard, a study in the Chinese Han population showed that polymorphisms of HDC gene were associated with breast cancer, further highlighting the clinical relevance of HDC in this disease." (PMID 31748740, 2020). "For instance, a study investigating the role of histamine and histamine H4 receptor (H4R) ligands in a TNBC model found that increased histidine decarboxylase (HDC) gene expression is associated with better relapse-free and overall survival in breast cancer patients." (PMID 39123356, 2024). "Previous studies revealed that polymorphisms of the HDC gene were significantly associated with breast cancer in the Chinese Han population, thus enhancing its role as a promising diagnostic or therapeutic target for breast cancer." (PMID 33282950, 2020). "Increased histidine decarboxylase (which produces histamine) gene expression is associated with better relapse-free and overall survival in breast cancer patients and histamine treatment reduces tumor growth and increased apoptosis in xenograft breast cancer models." (PMID 35433433, 2022). "In addition, higher expression of HDC was significantly associated with improved disease-free survival in all breast cancer patients as well as in TNBC patients, suggesting that histamine may reduce or delay metastatic breast cancer." (PMID 31748740, 2020). "In the present work, we first analysed the expression of the histamine-synthesising enzyme HDC in human breast cancer tissues." (PMID 31748740, 2020). "The aim of this study is to analyze the clinical associations of polymorphisms in HDC, HNMT and HRH3 with breast cancer." (PMID 24835231, 2014). "Collectively, these findings suggest that the reduced expression of HDC in breast cancer patients might be involved in cancer progression and could be associated with the prognosis of the disease." (PMID 31748740, 2020). "By using publicly available genomic data, we first investigated whether HDC could be a potential biomarker, which could correlate with breast cancer prognosis in terms of survival." (PMID 31748740, 2020). "Notably, the level of HDC mRNA expression in TNBC tissue was lower than in other breast cancer types." (PMID 31748740, 2020). "Based on the presented evidence, combining patients’ survival analysis and in vitro and in vivo studies in TNBC model, we conclude that HDC may be a potential prognostic biomarker in breast cancer that could complement routine histopathological analysis." (PMID 31748740, 2020). "Therefore, with respect to the notion that genetic factors contribute greatly to the risk and development of breast cancer, polymorphisms of HDC, HNMT, HRH3 and HRH4 are likely to be also associated with breast cancer risk." (PMID 24835231, 2014). "However, the associations between polymorphisms of HDC, HNMT, HRH3 and susceptibility to breast cancer are still unknown so far and need to be elucidated." (PMID 24835231, 2014). "Therefore, genes that encode HDC, HNMT and HRH3 are rationally considered as candidate genes associated with development of breast cancer that is believed to be a multiple gene-related disease and whose development was previously reported to be affected by these molecules." (PMID 24835231, 2014). "In addition, many studies have described the expression and activity of the histamine-synthesising enzyme histidine decarboxylase (HDC) in breast cancer patients, but the results are somehow controversial, while its prognostic relevance in breast cancer is still not known." (PMID 31748740, 2020).
melanoma (5 papers, 2017 to 2024). A malignant, usually aggressive tumor composed of atypical, neoplastic melanocytes. "In various cancers, including melanoma and non-small cell lung cancer, the activity of histidine decarboxylase, an enzyme that is highly involved in histamine secretion, has been reported to be significantly increased in laboratory studies." (PMID 38932232, 2024). "On one side, the use of specific anti-sense oligonucleotides against histidine decarboxylase (HDC) decreased the proliferation rate of human melanoma cells, while over-expression of HDC markedly accelerates tumor growth and increases metastatic colony-forming potential in mouse melanoma." (PMID 28460440, 2017). "The elevated expression of HDC was also identified in human melanoma and small-cell lung carcinoma." (PMID 28168355, 2017). "This observed effect may be due to differences in the histamine catabolism and/or in histidine decarboxylase activity between nevi and melanomas." (PMID 28460440, 2017). "HDC has been reported to expressed in melanoma and human small cell lung carcinoma." (PMID 28415579, 2017). "In this context, results indicate that although histidine decarboxylase levels are significantly higher in melanomas than in nevi, and it is expressed in a greater number of malignant respect to benign lesions, the content of intracellular histamine was similar in both tissues." (PMID 28460440, 2017).
asthma (3 papers, 2010 to 2026). "Moreover, interactions with other polymorphisms associated with histamine metabolism (eg. histidine decarboxylase gene, histamine receptors genes) may influence the risk of asthma development." (PMID 21040557, 2010). "After adjusting for confounding factors such as gender and age, these five genes (CEBPE, HDC, IRAK3, PRR4, and SOD2) were still independent risk factors for asthma." (PMID 41602038, 2026). "By conducting bioinformatics analysis, we identified five genes (CEBPE, HDC, IRAK3, PRR4, and SOD2) associated with asthma." (PMID 41602038, 2026). "To determine the role of these key genes in the occurrence of asthma caused by environmental pollution, we provided strong evidence that the expression of genes of interest (CEBPE, HDC, IRAK3, PRR4, and SOD2) increased significantly in 160 participants with asthma." (PMID 41602038, 2026). "The results revealed that five genes of interest (CEBPE, HDC, IRAK3, PRR4, and SOD2) showed a strong mediating effect between PM2.5 and the onset of asthma, suggesting that PM2.5 may alter the expression of these genes, thereby causing the onset of asthma." (PMID 41602038, 2026). "Finally, five genes (CEBPE, HDC, IRAK3, PRR4, and SOD2) were identified as overlapping features across all three algorithms, as illustrated in the Venn diagram, and were thus considered robust candidate biomarkers for asthma." (PMID 41602038, 2026).
colon cancer (3 papers, 2017 to 2020). "CEACAM1 is a metastasis-associated protein and histidine decarboxylase (HDC) is involved in the growth of colon tumors." (PMID 28402947, 2017). "Histamine could suppress colorectal tumorigenesis and severity of inflammation-associated colon cancer in HDC KO mice." (PMID 32037496, 2020).
narcolepsy (3 papers, 2015 to 2024). A sleep disorder characterized by a tendency for excessive sleepiness during the day which occurs even after adequate sleep in the nighttime. "The finding of a similar reduction in the variability of breath duration during R in HDC-KO and DM compared with WT indicates a potential for histamine deficiency to modulate the respiratory phenotype of narcolepsy, at least during R, in the sense of a greater regularity of breathing." (PMID 26474479, 2015). "The evidence became stronger with the report that histidine decarboxylase (HDC) knockout mice, which lack histamine, display increased paradoxical sleep, sleep-wake cycle modifications, and are unable to remain awake under diurnal high vigilance (narcolepsy)." (PMID 31024298, 2019). "The number of neurons within the TMN whose ability to synthesize HA from L-histidine is confirmed by the expression of histidine decarboxylase (HDC) is estimated to be in the range of 60,000–125,000 and may change in various disorders (e.g., increased in narcolepsy)." (PMID 39337347, 2024). "Sleep attacks fragmenting wakefulness, cataplexy, excess rapid-eye-movement sleep (R) during the activity period, and enhanced increase of arterial pressure during R, which are hallmarks of narcolepsy in mice, did not occur in HDC-KO, whereas they were observed in DM mice." (PMID 26474479, 2015). "To address this question, we tested whether some of narcolepsy signs would be detected in mice lacking histamine signaling (HDC-KO)." (PMID 26474479, 2015).
osteoporosis (3 papers, 2012 to 2024). A condition of reduced bone mass, with decreased cortical thickness and a decrease in the number and size of the trabeculae of cancellous bone (but normal chemical composition), resulting in increased fracture incidence. "Additionally, studies on histidine decarboxylase knockout mice, an enzyme necessary for histamine production, showed a reduced number of osteoclasts and increased bone formation, indicating a protective effect against osteoporosis." (PMID 39596937, 2024).
Sepsis (3 papers, 2016 to 2023). Sepsis is defined as life-threatening organ dysfunction caused by a dysregulated host response to infection. "Sepsis-induced abnormal cytokine production and multiple organ injury (lung, liver, and kidney) were significantly reduced in HDC-knockout mice compared to WT C57BL/6 J mice." (PMID 36823620, 2023). "In HDC KO mice, the injection of lipopolysaccharide (LPS), a model of sepsis, in living mice led to lower increases in IL-6 in serum or liver (heart was not reported) than in WT." (PMID 34987383, 2021). "H1R−/−/H2R−/− mice apparently behaved similar to HDC knockout mice in reducing sepsis-related pathological changes." (PMID 27822777, 2016). "In H2R KO mice and HDC KO mice, sepsis was more lethal than in WT mice." (PMID 34987383, 2021). "Innate immunity and inflammation, such as ZDHCC19, ALOX15, FCER1A, HDC, PRSS33, and PCSK9, were upregulated in elderly ICU patients with sepsis." (PMID 36823620, 2023). "On day-8 in elderly ICU patients with sepsis, genes related to innate immunity and inflammation, such as ZDHCC19, ALOX15, FCER1A, HDC, PRSS33, and PCSK9, were upregulated." (PMID 36823620, 2023). "We applied HDC gene knockout (HDC−/−) mice, lacking histamine, to investigate the effect of histamine deficiency on the pathophysiology of CLP-induced sepsis." (PMID 27822777, 2016).
depression (2 papers, 2021 to 2024). "In our previous studies, we found that HDC mRNA was significantly decreased both in depression patients and in chronic stress model mice." (PMID 39720595, 2024). "The downregulation of HDC expression led to the activation of the IL-6/STAT3/S100A9 pathway, stimulating Th17 cells to secrete IL-17A, thereby promoting ovarian cancer progression, which suggests that HDC may be a potential therapeutic target for the comorbidity of ovarian cancer and depression." (PMID 39720595, 2024). "For instance, the oncogene S100A9 was upregulated while the tumor suppressor genes HDC, AKAP12, SFRP5, and ALOX15 were downregulated in depression groups." (PMID 34650925, 2021).
Hypertension (2 papers, 2019 to 2025). The presence of chronic increased pressure in the systemic arterial system. "In this study, we employed histidine decarboxylase (HDC)‐Cre transgenic rats, Hrh4‐knockout (KO) mice, and two hypertensive models (SHRs and stress‐induced hypertensive rats) to investigate H4R as a potential central target for hypertension management." (PMID 41017599, 2025).
liver fibrosis (2 papers, 2024 to 2025). "In a mouse model, knocking out L-histidine decarboxylase (HDC) led to reduced histamine levels, resulting in alleviated biliary damage and liver fibrosis." (PMID 39736991, 2024). "The study suggests that HDC knockout improves the progression of liver fibrosis." (PMID 39991151, 2025).
tic disorder (2 papers, 2015 to 2017). Disorders characterized by recurrent TICS that may interfere with speech and other activities. "Histamine dysregulation has been identified as a rare genetic cause of tic disorders; mice with a knockout of the histidine decarboxylase (Hdc) gene represent a promising pathophysiologically grounded model." (PMID 28117842, 2017).
airway hyperresponsiveness (1 paper, 2018). "In addition, we demonstrated that chlamydial infection was sufficient to elicit mRNA expression of HDC, indicating the production of histamine within the lung, which most likely contributes to airway hyperresponsiveness." (PMID 30374355, 2018).
anaphylaxis (1 paper, 2025). An acute hypersensitivity reaction that occurs from exposure to an allergen. "Unlike IgE-mediated anaphylaxis, Scombroid syndrome results from histamine production by bacterial histidine decarboxylase in improperly preserved fish." (PMID 40610892, 2025).
atherosclerosis (1 paper, 2024). A disease characterized by the build-up of fatty material and calcium deposition in the arterial wall resulting in partial or complete occlusion of the arterial lumen. "Among major findings, our results suggest a role of triglyceride-associated and mast-cell functional genes FCER1A, MS4A2, GATA2, HDC, and HRH4 in atherosclerosis risks." (PMID 39276247, 2024).
atrophic gastritis (1 paper, 2024). "In humans with atrophic gastritis, ECL hyperplasia has been associated with an increase in the amount of histamine produced in the fundus of the stomach and increased activity of histidine decarboxylase (HDC), the enzyme which synthesizes histamine." (PMID 38474790, 2024).
Atrophy (1 paper, 2022). Any weakening or degeneration, especially through lack of use. "Numerous studies have identified hDC as risk factors for progression to atrophy in several studies." (PMID 36079043, 2022).
chlamydial infection (1 paper, 2018). "In order to determine if chlamydial infection could induce histamine production in neutrophils, BAL neutrophils were isolated and purified as described in the methods section and assessed for mRNA expression of HDC using RT-PCR." (PMID 30374355, 2018).
colorectal adenocarcinoma (1 paper, 2018). The most common type of colorectal carcinoma. "Surgically resected colorectal adenocarcinomas showed an increase in both histamine concentration and histidine decarboxylase with increased staging." (PMID 29330550, 2018).
colorectal cancer (1 paper, 2020). A primary or metastatic malignant neoplasm that affects the colon or rectum. "Higher activities of histidine decarboxylase might result in decreasing histidine since decarboxylation of histidine by this enzyme in the colorectal cancer has been reported 76-77." (PMID 32201524, 2020).
COVID-19 (1 paper, 2021). A disease caused by infection with severe acute respiratory syndrome coronavirus 2. "Interestingly, other MC-specific genes, such as SIGLEC6, HDC, KIT, and others were not increased in COVID-19 lung tissue." (PMID 33777047, 2021).